JAK3 (Janus kinase 3)
Diseases named in the same sentence as JAK3 in open-access papers (continued):
Sharing a sentence is not in itself a finding about the gene and the disease.
leukemia (40 papers, 2012 to 2025). A malignant (clonal) hematologic disorder, involving hematopoietic stem cells and characterized by the presence of primitive or atypical myeloid or lymphoid cells in the bone marrow and the blood. "WES identified four mutations at the Pax5 locus, as well as other leukemia hotspot mutations such as Nras:p.Q61H and Jak3:p.R653H." (PMID 41283237, 2025). "Several hematopoietic transcription factors have been found to co-operate with JAK3 GOF mutations across a range of leukemia types." (PMID 38474223, 2024). "Adopting the SWISS-MODEL structures, many of the JAK1 and JAK3 leukemia-driving variants are located within dynamic regions including small loops." (PMID 37834019, 2023). "JAK2 and JAK3 are associated with the pathogenesis of leukemia and common lymphoid-derived illnesses." (PMID 36677654, 2023). "We found that PHF6 mutations frequently coexist with JAK3 mutations in T-ALL patients, and Phf6 comutation with JAK3 can drive aggressive leukemia in mice." (PMID 34465864, 2022). "Mutations in JAK3 have been found in patients with various leukemia/lymphoma of mostly lymphocytic subtype." (PMID 33672930, 2021). "Similar to JAK1 and JAK2 mutations, the most prevalent mutations in JAK3: M511I, A573V, and R657Q can drive several types of leukemia." (PMID 33672930, 2021). "As JAK3 mutants are dependent on JAK1 signaling for their cellular transformation, it is possible to use both JAK1/JAK2 and JAK3‐selective inhibitors in JAK3 mutation–positive leukemia." (PMID 35846099, 2021). "Treating these mice with AZD1208 (a PIM1 inhibitor) resulted in an increased attenuation of JAK3-mutated leukaemia compared with that seen following ruxolitinib treatment." (PMID 31792348, 2020). "Various types of leukaemia and lymphoma have been recently identified from the extensive studies of human patients and mouse models that had persistent activation of JAK3 signalling with somatic mutations." (PMID 32558259, 2020). "Previously, gain-of-function mutations have been reported in JAK1 or JAK3 in some neoplasms, leukemia, breast cancer, lung cancer, hepatocellular carcinoma, and NK-lymphoma cells." (PMID 30123428, 2018). "None of these mutations are classified as being clinically pathogenic by the dbSNP database, and only the JAK3 mutation is present in the COSMIC database (in leukemias, glioblastomas and cutaneous squamous cell carcinoma) which is an activating mutation." (PMID 29700339, 2018). "The important role of JAK3 mutations in leukemia has become increasingly clear in recent years." (PMID 35111683, 2021). "By targeting both JAK1 and JAK3 in JAK3 mutant leukemia cells, it may be very difficult for the leukemia cells to overcome this block by just one mutation." (PMID 26208852, 2015). "Moreover, an activating Jak1 p.F837V variant was identified in one of the leukemic samples, which again highlights the importance of the JAK/STAT-signaling pathway in Pax5+/− leukemias, as shown for Jak1 and Jak3 mutations in the Pax5+/− delayed-exposure B-ALL3,25." (PMID 37620322, 2023). "Case 1 harbors an activating missense mutation in JAK3 (p.V722I, COSV71685519) that is related to various types of lymphomas and leukemias, and found recurrently in other cancers as well." (PMID 40404986, 2025). "In contrast, the overexpression of HOXA genes, particularly HOXA9, has been observed concurrently with JAK3 GOF mutations in T-ALL with HOXA9 overexpression co-operating with the JAK3 M511I mutation to elicit a short latency, aggressive leukemia in mice." (PMID 38474223, 2024).
leukemia (continued). "A second hit (targeting Jak3 in our model) created a dominant survival signal, probably founding overt preB-I leukemia." (PMID 35459909, 2022). "However, the role(s) of PHF6 mutations in JAK3-driven leukemia remain unclear." (PMID 34465864, 2022). "In order to investigate the effects of JAK3 inhibitors on leukemia cells, we selected the approved JAK inhibitors and a panel of hematological malignancy cells." (PMID 35111683, 2021). "For instance, NC1153 can inhibit JAK3 specifically and induce the apoptosis of certain leukemia/lymphoma cell lines." (PMID 34721544, 2021). "Different types of leukemia harbor genomic aberrations in all four JAKs (JAK1, JAK2, JAK3, and TYK2), most of which are activating somatic mutations and less frequently translocations resulting in constitutively active JAK fusion proteins." (PMID 33672930, 2021). "We recently showed that most JAK3 mutations, identified in T-ALL patient samples, caused leukemia in a mouse model." (PMID 26208852, 2015). "It will be of interest to investigate both JAK1 and JAK3 kinase inhibitors as targeted agents for these leukemias." (PMID 26208852, 2015). "Primary and secondary transplanted mice were subsequently used to test the efficacy of the JAK3-selective inhibitor, tofacitinib (Xeljanz, Pfizer), to treat leukemia progression." (PMID 26208852, 2015). "Because JAK3 is overexpressed in leukemia, researchers have sought to identify a drug that was capable of fitting into the JAK3 catalytic domain." (PMID 24170986, 2013). "In T-ALL, over 40% of patients with JAK3 GOF mutations also possessed PHF6 LOF mutations, with this cohort showing reduced survival, while PHF6 inactivation in mice accelerated cell transformation mediated by JAK3 M511I, inducing an aggressive form of leukemia." (PMID 38474223, 2024). "This interaction suggests PHF6’s essential function in leukemia development and underscores the potential of combining JAK3 and MDM2 inhibitors as a targeted therapy for T-ALL patients with co-mutation of PHF6 and JAK3." (PMID 38813086, 2024). "Moreover, we found that some genes are also important for leukemia development (Jarid2, Metap2, Jak3, Pla2G15, Zfp384, Casp8 and Dpf2)." (PMID 37700325, 2023). "Together these data are consistent with constitutively active JAK3 eliciting a mild lymphoproliferative disorder rather than overt leukemia, with mutation of a single allele sufficient to achieve this." (PMID 35622134, 2022). "Considering the crucial role of JAKs in the development and function of hematopoietic cells, it is not surprising that JAK1, JAK2, and JAK3 mutations are often found in leukemia." (PMID 33672930, 2021). "JAK3 is a cytoplasmic non-receptor tyrosine kinase that plays a role in cytokine pathways and growth factor receptors, and its mutation is frequently described in cancers such as lymphomas and leukemias." (PMID 40573233, 2025). "Interestingly, leukemia 241 showed concomitant JAK3 (p.R653H) and NRAS (p.G13S) activation." (PMID 40394211, 2025). "AT9283, originally identified as a multi-target kinase inhibitor against aurora A, Aurora B, JAK3, JAK2, and Abl, has been reported to be effective drug against leukemia cells, myeloproliferative diseases and various solid cancer cell lines." (PMID 38414025, 2024). "Most of these genes were associated with cancers of metabolic systems (DUSP6, SGK1, BMP4, RASGRF1, GDF15) followed by breast cancer (CACNA2D3, ITGB7), cancers of the central nervous system (PRKCA), or leukemia (MECOM, JAK3)." (PMID 36624125, 2023). "Here, the cooperation between JAK3 activation and PHF6 inactivation is examined in leukemia patients and in mice models." (PMID 34465864, 2022).
leukemia (continued). "Furthermore, combination therapy with a JAK3 inhibitor (tofacitinib) and a MDM2 inhibitor (idasanutlin) reduces the Phf6 KO and JAK3M511I leukemia burden in vivo." (PMID 34465864, 2022). "So-called passenger mutations, such as some JAK3 kinase domain mutations and the majority of mutations in the FERM/SH2 domain of JAK3, do not contribute to cellular transformation nor leukemia development." (PMID 34066732, 2021). "Thus, AG-490 suppresses several signaling pathways, including IL-2-mediated signaling, which is upstream of JAK3 and STAT5A and B. Generally, AG-490 can be used to control the abnormal constitutive activation of JAK2 in leukemia cell lines." (PMID 24170986, 2013). "Constitutive JAK3 activation has been found in different lymphoid malignancies, including mantle-cell lymphoma, Burkitt lymphoma, anaplastic large-cell lymphoma, HTLV-1-induced adult T-cell lymphoma/leukemia, and CTCL, but the mechanisms of constitutive JAK3 activation are still largely unknown." (PMID 37830594, 2023). "While it is not clear whether specific JAK3 inhibition would be beneficial for leukemia therapy, JAK3 T-ALL mutants have been found to be sensitive to inhibition." (PMID 33672930, 2021). "Pax5 heterozygous mice do not develop leukemia when housed in specific pathogen free (SPF) conditions however they are prone to precursor B ALL when exposed to common pathogens and sequencing of these leukemias identified recurrent Jak3 mutations." (PMID 34484175, 2021). "Whereas the A572T mutation was not described before, JAK3 amino acid A572 was found mutated into a V (A572V mutation) in T-cell leukemia, T-cell lymphoma, and AML, and this A572V mutant transformed cytokine dependent hematopoietic cells and induced leukemia in mice." (PMID 22675565, 2012).
autoimmune disease (33 papers, 2011 to 2025). A disorder resulting from loss of function or tissue destruction of an organ or multiple organs, arising from humoral or cellular immune responses of the individual to their own tissue constituents. "Many of the cytokines involved in LN and other autoimmune diseases, including IL-17, signal through receptors associated with JAKs, and CP-690,550 targets JAK3, which plays a pivotal role in the beginning of the inflammatory cytokine signaling pathway." (PMID 27278657, 2016). "Thus, JAK3 has become an ideal target for the treatment of inflammatory and autoimmune diseases including hair loss." (PMID 38637842, 2024). "It is noteworthy that mutations in JAK3’s Cys909 residue may result in the constitutive activation of the kinase, which can contribute to the development of autoimmune disorders." (PMID 37570884, 2023). "JAK1 is closely related to inflammation, cancer, immunity, and other diseases, JAK2 is primarily related to diseases of the blood system, and JAK3 is related to a variety of autoimmune diseases." (PMID 40746612, 2025). "While pan-JAK inhibitors such as tofacitinib and ruxolitinib have demonstrated clinical success in autoimmune diseases, selective inhibition of JAK3 remains limited because of the high sequence similarity within ATP-binding pockets of JAK1, JAK2, and JAK3." (PMID 41385500, 2025). "JAK1 and JAK3, through gamma phosphorylation, play a major role in the signal transduction of several pro-inflammatory cytokines, explaining their involvement in autoimmune disorders." (PMID 39189018, 2024). "Based on the structural and functional characteristics of JAKs, as well as specific tissue distribution, JAK3, in particular, has emerged as an ideal target for the treatment of inflammatory or autoimmune diseases as previously demonstrated." (PMID 37624299, 2023). "Disruption of different components in IL-2 signaling pathway, including CD25, CD122, Janus kinase 3, and STAT5, leads to compromised Treg generation associated with autoimmune diseases." (PMID 37436991, 2023). "Ruxolitinib (JAK1/JAK2), Tofacitinib (JAK1/JAK3) and Ritlecitinib (JAK3 selective) were selected in the current study based on their clinical efficacies in treating lymphoma and autoimmune diseases." (PMID 35911775, 2022). "CS12192 is a novel JAK3 inhibitor discovered by Chipscreen Biosciences for the treatment of autoimmune diseases." (PMID 36362183, 2022). "This residue has been targeted in JAK3 drug discovery, and one highly selective covalent JAK3 inhibitor is currently in phase 3 clinical trials against autoimmune diseases." (PMID 33672930, 2021). "The major drawback of these JAK1 and JAK3 inhibitors affecting the inflammatory response is that they can induce autoimmune diseases (thyroiditis or myocarditis) or can prime the development of many infections in patients with MPN." (PMID 29399328, 2018). "Decernolitinib is also a potent and selective inhibitor of JAK3 developed as a second-generation inhibitor in autoimmune diseases, particularly in RA." (PMID 29399328, 2018). "Clinical use of STAT5-activating cytokines and growth factors (e.g. IL-2, erythropoetin) is now commonplace and the recent approval of Jak3 inhibitors for the treatment of autoimmune disease and malignancy points to sustained interest in this pathway." (PMID 26999798, 2016). "The results of our present study clearly show that selective inhibition of JAK3 is ready to use as a new treatment for LN in clinical practice, given its profile and good tolerability in autoimmune diseases." (PMID 27278657, 2016). "Tofacitinib (Tofa) is an inhibitor of Janus Kinase 3, developed for the treatment of autoimmune diseases and for the prevention of transplant rejection." (PMID 24416411, 2014). "Janus kinase 3 (JAK3) is an essential enzyme for treating autoimmune diseases, including RA." (PMID 37570884, 2023).
autoimmune disease (continued). "Thus, JAK inhibitors targeting preferentially JAK1 and JAK3 have been developed to treat inflammation, autoimmune diseases, and graft-versus-host disease." (PMID 29399328, 2018). "Specific inhibition of JAK3 signaling cascade by anti-γc antibody could eliminate hyperactivated NK cells and suppress NK autoreactivity in the culture, which may serve as a potent and safer strategy to treat autoimmune diseases." (PMID 38106519, 2023). "Therefore, selective targeting of JAK3 has attracted many interests to prevent transplant rejection, treat various autoimmune diseases such as rheumatoid arthritis, ankylosing spondylitis (AS), and psoriasis, and reduce the adverse effects of JAK1 and JAK2 inhibition." (PMID 35628248, 2022). "Since the function of JAK3 in cell signaling is usually to promote immune responses, inhibiting JAK3’s function offers a unique possible therapeutic potential for the treatment of patients with abnormal immune responses, including potential application in the treatment of autoimmune diseases." (PMID 30974919, 2019). "Indeed, mice deficient in JAK3 or STAT5A/B develop a severe immunodeficiency that is followed by multiple organ autoimmune diseases, a decreased number or the absence of CD4+CD25+ nTreg in their peripheral lymphoid organs, and early death." (PMID 21647403, 2011). "These first-generation inhibitors simultaneously bind to JAK1, JAK2, JAK3, TYK2, and other homologous targets, thereby blocking multiple downstream signaling pathways, thereby treating a variety of autoimmune diseases." (PMID 40746612, 2025). "Ritlecitinib mainly targets JAK3, a direct downstream molecule of CD132, and has shown promising results in autoimmune diseases such as IBD, pemphigus, and vitiligo, indicating potential applications for 2D4." (PMID 39551768, 2024). "JAK3 differs from other JAK family members in terms of tissue distribution and functional properties, making it a promising target for autoimmune disease treatment." (PMID 35628248, 2022). "To date, no selective JAK3 inhibitor has yet been approved for the treatment of inflammatory and autoimmune diseases." (PMID 37624299, 2023). "In addition, favilipid A inhibited by 58–48% three kinases (JAK3, IKKβ, and SYK) involved in the regulation of the immune system, suggesting a potential use for treatment of autoimmune diseases, hematologic cancers, and other inflammatory states." (PMID 36827099, 2023). "Interestingly, direct blockade of downstream JAK3 activity with anti-γc antibody could suppress γc cytokine-induced NK cell activation but maintains immunity against tumor cells, suggesting that antibody might offer a safer strategy to treat NK cell-mediated autoimmune diseases." (PMID 38106519, 2023). "Although JAK3 has been identified as a potential therapeutic target in autoimmune disease, its role in rheumatoid synovitis has not been fully elucidated." (PMID 21548952, 2011). "JAK1 functions in concert with JAK3 to mediate downstream γc signaling; furthermore, a number of key inflammatory cytokines, such as type I and type II IFN, might depend on JAK1-mediated signaling in several autoimmune disorders, including AA." (PMID 36203601, 2022). "Indeed, mice deficient in IL-2, IL-2R, JAK-3, or STAT5A/B have an absent or reduced number of thymic and peripheral CD4+ CD25+ nTreg and consequently develop multiple organ autoimmune diseases." (PMID 21647403, 2011). "Unlike autoimmune diseases like psoriasis or alopecia areata, where only one JAK pathway is dysregulated, AD involves increased signaling through all four JAKs (JAK1, JAK2, JAK3, and TYK2)." (PMID 40151746, 2025). "Although there are no documented reports of JAK3 inhibitor-based therapy for SLE, we posit that 2D4 may exhibit greater efficacy in autoantibody-mediated autoimmune disease than JAK3 inhibitors." (PMID 39551768, 2024).